TOR1A (torsin family 1 member A)
Description:
Protein with chaperone functions important for the control of protein folding, processing, stability and localization as well as for the reduction of misfolded protein aggregates. Involved in the regulation of synaptic vesicle recycling, controls STON2 protein stability in collaboration with the COP9 signalosome complex (CSN). In the nucleus, may link the cytoskeleton with the nuclear envelope, this mechanism seems to be crucial for the control of nuclear polarity, cell movement and, specifically in neurons, nuclear envelope integrity. Participates in the cellular trafficking and may regulate the subcellular location of multipass membrane proteins such as the dopamine transporter SLC6A3, leading to the modulation of dopamine neurotransmission. In the endoplasmic reticulum, plays a role in the quality control of protein folding by increasing clearance of misfolded proteins such as SGCE variants or holding them in an intermediate state for proper refolding. May have a redundant function with TOR1B in non-neural tissues.
Synonyms: DQ2; DYT1; AMC5
Tractability: Small molecule: a structure with a bound ligand is known. Antibody: UniProt places it where antibodies can reach, with high confidence; UniProt predicts a signal peptide or a membrane-spanning region. PROTAC: ubiquitination databases record sites on it; its protein half-life has been measured.
Gene: Protein-coding gene on chromosome 9 (129,812,942 to 129,824,244, reverse strand). Ensembl gene ENSG00000136827.
Subcellular location: Endoplasmic reticulum lumen; Nucleus membrane; Cell projection, growth cone; Cytoplasmic vesicle membrane; Cytoplasmic vesicle, secretory vesicle; Cytoplasmic vesicle, secretory vesicle, synaptic vesicle; Cytoplasm, cytoskeleton
Subcellular location (Human Protein Atlas): Nuclear membrane; Vesicles
Pathways (Reactome):
Vesicle-mediated transport: Cargo recognition for clathrin-mediated endocytosis
Gene Ontology:
Molecular function: ATP hydrolysis activity; ATP-dependent protein folding chaperone; cytoskeletal protein binding; identical protein binding; kinesin binding; protein binding; ATP binding; misfolded protein binding
Biological process: cell adhesion; intermediate filament cytoskeleton organization; neuron projection development; positive regulation of synaptic vesicle endocytosis; protein deneddylation; protein folding; protein localization to nucleus; regulation of dopamine uptake involved in synaptic transmission; regulation of protein localization to cell surface; synaptic vesicle membrane organization; synaptic vesicle transport; ERAD pathway; nuclear envelope organization; nuclear membrane organization; wound healing, spreading of cells; response to oxidative stress
Cellular component: endoplasmic reticulum; endoplasmic reticulum lumen; endoplasmic reticulum membrane; extracellular exosome; membrane; nuclear membrane; synaptic vesicle; cytosol; growth cone; nuclear envelope; secretory granule; cytoplasm; cytoplasmic vesicle membrane; cytoskeleton; endomembrane system; nucleus; transport vesicle
Genetic constraint (gnomAD): Loss-of-function variants: 18 observed, 31.78 expected, observed/expected ratio (o/e) 0.57, 90% interval 0.39 to 0.84. The upper end of that interval is the gene's LOEUF score, 0.84, which puts it in group 3 of 6, group 1 being the genes least tolerant of losing a copy. Missense variants: 375 observed, 429.59 expected, observed/expected ratio (o/e) 0.87, 90% interval 0.8 to 0.95. Synonymous variants: 168 observed, 167.18 expected, observed/expected ratio (o/e) 1, 90% interval 0.88 to 1.14.
Homologues: Orthologues: chimpanzee TOR1A (99% identical), dog TOR1A (93% identical), pig TOR1A (92% identical), mouse Tor1a (91% identical), guinea pig TOR1A (90% identical), rat Tor1a (87% identical), macaque C15H9orf78 (84% identical), rabbit TOR1A (84% identical), zebrafish tor1 (57% identical), zebrafish tor1l2 (47% identical), zebrafish tor1l1 (46% identical), zebrafish tor1l3 (45% identical), and 4 more. Paralogues in human: TOR1B (67% identical), TOR2A (40% identical), TOR3A (39% identical), TOR4A (23% identical).
Diseases named in the same sentence as TOR1A in open-access papers:
TOR1A is named in the same sentence as 95 diseases in open-access papers, as found by Europe PMC text mining. Sharing a sentence is not in itself a finding about the gene and the disease. The quoted sentences say what the papers report.
Dystonia (212 papers, 2006 to 2026). An abnormally increased muscular tone that causes fixed abnormal postures. "In humans with the Tor1a mutation, dystonia typically manifests around 12 years of age (though some individuals develop or are diagnosed with dystonia later in life)." (PMID 41476021, 2026). "The most common inherited dystonia is associated with TOR1A variants, accounting for 16–53% of generalized dystonia in the non-Jewish population and up to 90% in the Ashkenazi Jewish due to a founder effect." (PMID 40584247, 2025). "For example, in DYT-TOR1A dystonia, an autosomal dominant hereditary condition, there is a penetrance of 30% following a heterozygous mutation in the TOR1A gene." (PMID 38500932, 2024). "Pathogenic variants in TOR1A have been identified and associated with this type of dystonia that is further characterized by tremor, hypotonia and Writter’s cramp." (PMID 39732776, 2024). "One study found that students with the DYT- TOR1A gene mutation reported worsening dystonia symptoms before important exams." (PMID 37638318, 2023). "Experimental studies on the mouse models of DYT1 (Tor1A)-associated dystonia provide compelling evidence of genetic predisposition for a link between peripheral injury and dystonia." (PMID 37008994, 2023). "BSP alone or in combination with dystonia in other anatomical segments has been reported in patients with deleterious variants in TOR1A, THAP1 and GNAL." (PMID 38076033, 2023). "Almost all patients with TOR1A-related dystonia harbor the same mutation, an in-frame GAG deletion (ΔGAG) in the last of its 5 exons." (PMID 37638318, 2023). "The THAP1 gene encodes a ubiquitously expressed transcription factor consisting of 213 amino acids and is putatively regulating the expression of various target genes, including TOR1A, the gene mutated in another form of dystonia, and THAP1 itself." (PMID 38835919, 2022). "The first dystonia gene, TOR1A (also known as DYT1 or DQ2), which causes systemic dystonia with average age of onset at 13, was discovered in 1997." (PMID 34276779, 2021). "At least two different genetic dystonia forms are currently known to be caused solely or primarily by such single founder variants: X-linked dystonia–parkinsonism (XDP; DYT/PARK-TAF1) and TOR1A-variant related isolated dystonia (DYT-TOR1A)." (PMID 33876307, 2021). "Mutations affecting the LAP1 or TOR1A interaction result in dystonia, muscular dystrophy, cardiomyopathy, and deafness." (PMID 34659373, 2021). "The DYT1 dystonia is a severe early-onset inherited dystonia caused by a GAG deletion (ΔGAG) in the gene TOR1A of torsin A (TA), which is responsible for the loss of a residue of glutamic acid in the carboxy-terminal region." (PMID 33445430, 2021). "The DYT1 dystonia is a severe early-onset inherited neurologic hyperkinetic movement disorder caused by a GAG deletion in the gene TOR1A of the torsin A." (PMID 34575134, 2021). "DYT1 dystonia is caused by an in-frame TOR1A deletion mutation that results in removal of a single glutamic acid residue (ΔE) from the torsinA protein." (PMID 33616084, 2021). "From a genetic standpoint, the autosomal-dominant inheritance of DYT1 dystonia has long been considered to result from a dominant negative effect of the mutant TOR1A(ΔE) allele." (PMID 32204310, 2020). "DYT-TOR1A is a generalized early onset dystonia with autosomal dominant inheritance caused by mutations in the TOR1A gene encoding torsinA (TOR1A)." (PMID 32239467, 2020). "Dystonia patients carrying different variants in the TOR1A gene have been reported, but the consensus has yet to be reached regarding their pathogenicity." (PMID 32670041, 2020). "Patients with DYT1 dystonia caused by the mutated TOR1A gene exhibit risk neutral behaviour compared to controls who are risk averse in the same reinforcement learning task." (PMID 32365120, 2020). "DYT-TOR1A is the most common inherited dystonia caused by a three nucleotide (GAG) deletion (dE) in the TOR1A gene." (PMID 32239467, 2020).
Dystonia (continued). "DYT1 dystonia is a dominantly inherited movement disorder that is caused by 3 bp in-frame deletion (ΔE mutation) in the TOR1A gene that encodes the torsinA protein." (PMID 32202496, 2020). "Given that primary dystonia caused by mutations of Tor1A or LAP1 seems to arise through a dysfunction of post-mitotic neurons, the function of Torsins is probably essential for the homeostasis of interphase cells." (PMID 33320087, 2020). "DYT1 dystonia is caused by a mutation in the TOR1A gene (c.904_906delGAG/907_909delGAG; p.Glu302del/Glu303del; TOR1AΔE), which encodes the protein torsinA; this mutation results in an in-frame deletion of a codon for glutamic acid (ΔE-torsinA)." (PMID 30403723, 2018). "Familial-isolated dystonias are predominantly inherited as incompletely penetrant autosomal dominant traits most frequently related to the DYT1 or DYT6 loci with mutations in TOR1A or THAP1, respectively." (PMID 29110692, 2017). "DYT1 dystonia is an early-onset, hyperkinetic movement disorder caused by a deletion in the gene TOR1A, which encodes the protein torsinA." (PMID 28659770, 2017). "Quite a few polymorphisms across TOR1A gene have been examined for possible association with dystonia, but the results from candidate gene association studies (CGASs) remain conflicting." (PMID 28081261, 2017). "Thereafter, functional characterization of the growing number of the identified TOR1A variants in dystonia patients signifies the importance of the whole genetic variability across TOR1A gene." (PMID 28081261, 2017). "Odds ratios (ORs) were calculated in each study to estimate the influence of TOR1A SNPs genotypes on the risk of dystonia." (PMID 28081261, 2017). "The role of another SNP, in particular rs3842225 polymorphism, that is also located in TOR1A 3’-UTR region of exon has also been examined in dystonia patients, but with ambiguous results." (PMID 28081261, 2017). "Quite a few studies have been contacted to examine possible contribution of TOR1A variants to the risk of dystonia, but their results remain conflicting." (PMID 28081261, 2017). "In the present meta-analysis we aimed to study the effect of all available TOR1A gene SNPs on the risk of dystonia and its sub-phenotypes." (PMID 28081261, 2017). "DYT1 dystonia is a rare, dominantly inherited form of dystonia, caused almost exclusively by a specific deletion of three base pairs in the TOR1A gene." (PMID 27249418, 2016). "This lack of specificity stands in contrast with genetically based dystonias (such as mutations in Tor1A or Thap1), in which a predictable pattern of symptom site(s) is expected." (PMID 27171035, 2016). "The more widespread use of gene sequencing in dystonia patients has more recently uncovered a number of additional variants in TOR1A in patients with isolated dystonia." (PMID 28138320, 2016). "DYT1 dystonia is mainly caused by a 3 bp in-frame deletion in TOR1A resulting in a loss of glutamic acid (ΔE) in Tor1A." (PMID 27313903, 2016). "DYT1 dystonia is caused by a dominantly inherited mutation of the TOR1A gene that impairs function of the encoded protein torsinA." (PMID 26052670, 2015). "TOR1A (DYT1), the gene responsible for the most common primary hereditary dystonia, encodes torsinA, an AAA ATPase family protein." (PMID 25887123, 2015). "Dystonia linked to a 3 base pair deletion (ΔGAG) mutation in exon 5 of the TOR1A gene on chromosome 9q34.11 is called DYT1 dystonia." (PMID 25403864, 2014). "Sanger sequencing confirmed that all the cases harbour the ΔGAG mutation (p.303-/Glu304) in exon 5 of the TOR1A gene which is a recurring mutation in DYT1 dystonia." (PMID 25403864, 2014). "The first described mutation for generalized isolated dystonia was a GAG deletion in the Tor1a gene causing DYT-TOR1A (also known as DYT1)." (PMID 25120431, 2014). "Early onset isolated dystonia (DYT1) is linked to a three base pair deletion (ΔGAG) mutation in the TOR1A gene." (PMID 25403864, 2014).
Dystonia (continued). "To date, only one coding polymorphism in exon 4 of TOR1A (rs1801968), which encodes either aspartic acid (D) or histidine (H), has convincingly been shown to modify the risk of developing symptoms of dystonia." (PMID 23775978, 2013). "DYT1 dystonia is caused by mutation of the TOR1A gene, resulting in the loss of a single glutamic acid residue near the carboxyl terminal of TorsinA." (PMID 23028827, 2012). "The dystonia-causing mutation is a 3-bp deletion in the TOR1A gene, that deletes a glutamic acid residue in the C-terminal coding region of the protein torsinA." (PMID 23185535, 2012). "TOR1A (formally DYT1), the gene responsible for the most common primary hereditary dystonia, encodes torsinA, an AAA ATPase family protein." (PMID 22022556, 2011). "DYT1 dystonia is caused by a trinucleotide deletion of a GAG (ΔGAG) codon in the DYT1 (TOR1A) gene, which results in the loss of a glutamic acid residue in the C-terminal region of the torsinA protein." (PMID 21479250, 2011). "Mutations in Exons 1–4 and associations between dystonia phenotypes and TOR1A copy number variants and single nucleotide polymorphisms must be interrogated in future studies." (PMID 19284587, 2009). "Childhood-onset DYT1 dystonia is a severe movement disorder caused by a heterozygous ΔE mutation in TOR1A, yet the molecular mechanisms driving disease remain unclear." (PMID 41986297, 2026). "In addition, dysregulation of the integrated stress response has been observed in several monogenic forms of dystonia, including those associated with variants in TOR1A, THAP1, PRKRA, EIF2AK2, and SGCE genes, suggesting a converging pathogenic mechanism." (PMID 40724495, 2025). "Moreover, dystonia and arthrogryposis have already been associated with biallelic variants in TOR1A which are responsible for congenital multiplex arthrogryposis type 5." (PMID 41180161, 2025). "However, the genetic basis of the disorder remained elusive until 1997, when the TOR1A (DYT1) gene was identified as the cause of early-onset isolated dystonia." (PMID 40722357, 2025). "Furthermore, in animal models of dystonia, an increase in long-term potentiation and the loss of long-term depression have been reported at corticostriatal synapses of mutant human tor1a knock-in mice." (PMID 39329704, 2024). "It is a severe genetic form of dystonia caused by mutations in the TOR1A gene." (PMID 37638318, 2023). "The TOR2A homologue TOR1A was the first gene convincingly linked to isolated dystonia." (PMID 38076033, 2023). "Among the most common genes with mutations that cause dystonia are TOR1A, GNAL, SGCE, and THAP1." (PMID 35821365, 2023). "DYT- TOR1A dystonia is a genetic disorder caused by a mutation (ΔE mutation) in the TOR1A gene." (PMID 37638318, 2023). "These plasticity defects may lead to abnormal neuronal function, thereby causing symptoms of DYT- TOR1A dystonia." (PMID 37638318, 2023). "This study further extends our understanding of molecular mechanisms underlying dystonia, and establishes a new functional paradigm to evaluate the inhibitor of ER stress to compensate for mutant Tor1a, which may be beneficial for neuronal function." (PMID 34398825, 2021). "A few retrospective studies and a recent meta-analysis of mixed cohorts of inherited or idiopathic isolated dystonia patients reported that the TOR1A mutation-positive status was associated with a better DBS response, whereas the reasons underpinning suboptimal responses remained mostly unexplored." (PMID 32670041, 2020). "In DYT1 dystonia, TOR1A is associated with vesicles in axons and pre-synaptic terminals." (PMID 32112337, 2020). "DYT1 dystonia is caused by a three-base-pair deletion (ΔGAG) in the TOR1A gene." (PMID 29739751, 2018). "A ΔGAG deletion in Exon 5 of TOR1A was the first SV to be linked to isolated dystonia." (PMID 29770609, 2018). "TOR1A gene variants seem to be implicated in dystonia phenotype." (PMID 28081261, 2017).